SMAD3 (SMAD family member 3)
Diseases named in the same sentence as SMAD3 in open-access papers (continued):
Sharing a sentence is not in itself a finding about the gene and the disease.
liver fibrosis (continued). "Matrine prevented MCD diet-induced inflammation and fibrosis in the liver after 6 weeks of treatment, as demonstrated by a matrine-induced suppression of the increases in TNFα, CD68, MCP-1 and NLRP3, and hepatic fibrosis proteins (TGFβ, Smad3, and collagen 1) induced by MCD diet." (PMID 31068812, 2019). "Therefore, we concluded that IH reduced autophagy and alleviated liver fibrosis by downregulating the TGF-β1/Smad3 signaling pathway." (PMID 31467486, 2019). "Suppression of Smad3 in HSCs is known to inhibit the Col-1 expression and reduce liver fibrosis." (PMID 31467486, 2019). "In addition, we found that clusterin attenuates hepatic fibrosis by inhibiting the activation of hepatic stellate cells and Smad3 signaling pathways." (PMID 31739636, 2019). "Recent studies may demonstrate that p300/CBP functions as the regulator of liver fibrosis through modulating SMAD3 activity." (PMID 29862292, 2018). "Taken together, these findings suggest the possibility that p300/CBP may contribute to liver fibrosis by promoting acetylation of SMAD3 in high glucose condition." (PMID 29862292, 2018). "The effect of Cpd861 on p-Smad2, p-Smad3, and SnoN expression show that these proteins may be treatment targets for hepatic fibrosis." (PMID 29402324, 2018). "Interleukin 6 (IL6) stimulates the activation of STAT3 and increases collagen mRNA expression in HSCs, thus accelerating liver fibrosis via Stat3 phosphorylation that in turn activates transforming growth factor beta (TGFβ) signaling cascade through SMAD3 activation." (PMID 30346985, 2018). "Furthermore, Smad3 works as a transcriptional activator of the TGF-β signaling transduction that exacerbates hepatic fibrosis." (PMID 26938532, 2016). "In addition to increased tumor progression, Smad3+/−/VDD mice also exhibit increased liver fibrosis as indicated by Sirius red and α-smooth muscle actin (α-SMA) staining." (PMID 27456065, 2016). "We evaluated whether the downregulation of miR-29b in liver fibrosis was mediated by Smad3 and their potential interaction." (PMID 25356754, 2015). "Thus, miR-29b is a downstream target gene of Smad3 in liver fibrosis that is negatively regulated by TGF-β/Smad3 signaling." (PMID 25356754, 2015). "CCl4-induced liver fibrosis was rarely detected in Smad3−/− mice compared to Smad3+/+." (PMID 24304543, 2013). "Treatment of Smad3 KO mice with CCl4 for 4 weeks successfully induced moderate liver fibrosis." (PMID 24304543, 2013). "Strikingly, vitamin D receptor was demonstrated to be key in the control of liver fibrosis by affecting SMAD3-mediated transcriptional response in mouse model, supporting the notion that this pathway might be essential in the control of liver fibrosis." (PMID 24391588, 2013). "Based on our findings, we suggest that the Smad3 may play a critical role in hepatic fibrosis development mediated by the regulation of antioxidant gene expression and TGF-β signaling." (PMID 24304543, 2013). "TGFβ1 bound its receptor, phosphorylated Smad3, and accelerated liver fibrosis." (PMID 22471627, 2012). "Moreover, blockade or silencing of CD39 could block the TGF-β/Smad3 pathway, alleviating alcoholic hepatic fibrosis." (PMID 41109667, 2026). "Therefore, Smad3 plays a crucial role in liver fibrosis in response to TGF-β." (PMID 39968080, 2025). "Notably, in the untreated group, the protein expression levels of pro-fibrotic mediators TGF-β, p-Smad2, and p-Smad3 were markedly elevated compared with the healthy group in the CCL4‐induced liver fibrosis model, consistent with the hyperactivation of this pathway during fibrosis progression." (PMID 40483470, 2025). "Hence, the suppression of the TGF-β/Smad3 signaling pathway could be a successful approach to avert the stimulation of HSCs and diminish liver fibrosis." (PMID 38468370, 2024).
liver fibrosis (continued). "Furthermore, overexpression of FBN1 remarkably restored the cell proliferation and inhibited cell apoptosis as compared to control, suggesting that MFAP2 mediated TGF‐β/Smad3 signalling pathway and fibrotic markers during liver fibrosis by upregulating the expression of FBN1." (PMID 37635348, 2023). "Hepcidin also ameliorates liver fibrosis by inhibiting hepatic stellate cells (HSCs)’ activation, which facilitates liver fibrosis via the degradation of ferroportin in HSCs, increasing Akt phosphorylation and finally prohibiting TGFb1-inducible Smad3 phosphorylation." (PMID 37628834, 2023). "In addition, the results of the current study indicated that the hepatic level of smad-7 was significantly reduced by 58.0%, whereas hepatic levels of smad-3 and collagen a1 were raised by 4.5- and 6.3-fold, respectively in the liver fibrosis group compared to the control group." (PMID 34894966, 2022). "Furthermore, the activation of the TGF-β/Smad3 cascade enhanced the progression of liver fibrosis." (PMID 36232707, 2022). "However, Smad2 and Smad3 have a similar structure and are intensely activated in liver fibrosis, whereas Smad3 directly binds to DNA sequences that regulate a series of fibrogenic (collagen) target genes and markers (α-SMA and E-cadherin), which belongs to Smad3-dependent genes." (PMID 34307359, 2021). "Activation of p38 could increase the Smad3 phosphorylation in hepatic fibrosis." (PMID 33995055, 2021). "Thus, we concluded that PIAS4 might contribute to liver fibrosis by modulating SIRT1-depenent SMAD3 acetylation." (PMID 27323886, 2016). "Also, it has been reported that diminish of SMAD3 expression by siRNA could markedly hinder the liver fibrosis via disruption of TGF-β signaling." (PMID 26468346, 2015). "In addition, TGF-β1/Smad2 and Smad3 signal pathway was also the main pathway which could be regulated in liver fibrosis." (PMID 24860243, 2014). "Shuai et al146 identified a novel, purinergic mechanisms by which ectonucleoside triphosphate diphosphohydrolase-1/ENTPD1 (CD39)–mediated ATP-adenosine signaling regulates TGF-β/Smad3 signaling during HSC-T6 activation and alcohol-related liver fibrosis." (PMID 41109667, 2026). "AZ12601011 (a TGF-βR I inhibitor) directly binds to TGF-βR I, blocking Smad3 activation, inhibiting the TGF-β/Smad3 signaling pathway, and alleviating paraquat-induced liver fibrosis in mice." (PMID 40655154, 2025). "Ferulic acid, a naturally occurring phenolic acid compound, mitigates concanavalin-induced liver fibrosis by stimulating the Nrf2 signaling pathway while inhibiting NF-κB and the TGF-β/Smad3 signaling pathway." (PMID 40655154, 2025). "A recent study demonstrated that VDR ligands inhibit hepatic stellate cell activation and fibrosis, that VDR KO mice spontaneously develop liver fibrosis, and that VDR antagonizes SMAD3/TGF β1 activation of profibrotic genes." (PMID 41148797, 2025). "We concluded that alpha-pinene reduced CCl4-induced liver fibrosis by lowering oxidative stress, suppressing liver inflammation, and inhibiting TLR4/NF-κB, TGF-β/Smad3, and PI3K/Akt/mTOR signaling pathways." (PMID 39968080, 2025). "In the present study, after DMDD treatment, hepatic TGF-β, Smad2, and Smad3 were significantly downregulated, and COL1A1, α-SMA, and TIMP1 were key genes in liver fibrosis." (PMID 40453659, 2025). "In both in vitro and in vivo liver fibrosis model, it suppresses HSC activation by inhibiting TGF-β1/Smad3 pathway thus reduces α-SMA and collagen I expression as well as targets JAK2/STAT3 pathway to regulate cell proliferation and apoptosis." (PMID 41293246, 2025). "Another flavonoid, namely naringenin displayed preventative activity against dimethylnitrosamine (DMN)-induced liver fibrosis and at doses of 20, 50 and 100 mg/kg mediated through blockage of TGF-β-Smad3 and JNK-Smad3 signaling pathways." (PMID 40892759, 2025).
liver fibrosis (continued). "In liver fibrosis models, ghrelin reduced TGF-β1 levels and Smad3 phosphorylation, while in kidney and cardiac fibrosis, similar protective effects were observed." (PMID 39569809, 2024). "For example, a polysaccharide from the roots of Codonopsis pilosula can promote the activation of HSCs in vivo and in vitro through the combined action of TGF-β1/Smad3 and TLR4/NF-κB signaling pathways, eventually promote liver fibrosis." (PMID 39359922, 2024). "Transforming growth factor beta acts via canonical signaling that involves the activation of Smad3 by the TGF-β receptor, followed by the induction of hepatic fibrosis." (PMID 38434258, 2024). "SMAD2, SMAD3, SMAD4, and SMAD7 expression levels were measured to determine TGF-β1 related hepatic fibrosis." (PMID 39055873, 2024). "Specifically, GDF15 has been found to promote the activation of hepatic stellate cells, a key event in the development of liver fibrosis, by enhancing the expression of fibrotic markers and the phosphorylation of SMAD2 and SMAD3 proteins." (PMID 39697329, 2024). "Our study demonstrates that an interactive effect between QC and CS can effectively reduce liver fibrosis and steatosis by inhibiting the TGF-β/Smad3 signaling pathway in a diet-induced model of nonalcoholic steatohepatitis and fibrosis in rats." (PMID 39055878, 2024). "YQJPF can reverse liver fibrosis by inhibiting inflammation, suppressing oxidative stress, regulating the immunological response initiated by macrophages, inhibiting TGF-β/Smad3 signaling and regulating intestinal flora homeostasis." (PMID 38434258, 2024). "Salvianolic acid B has been reported to fight lung and liver fibrosis by inhibiting the overexpression of α-SMA, collagen-1, TGF-β1, and the phosphorylation of Smad3, a downstream target of TGF-β1." (PMID 38983912, 2024). "In the rat model of liver fibrosis, the results from the western blotting and qRT-PCR show that ghrelin administration can suppress the TGF-β1/Smad3 as well as NF-κB signaling pathways, indicating autophagy is inhibited to improve liver fibrosis." (PMID 38139082, 2023). "Firstly, in vitro activation of HSCs and CCl4-induced liver fibrosis models in mice showed that PTCH1 affects HSC activation through the Gli1 and Smad3 signaling pathways." (PMID 37056286, 2023). "At the same time, phosphorylated Smad2/Smad3 positively feeds back into the TGF-β pathway, exacerbating the development of liver fibrosis." (PMID 37056286, 2023). "The in vitro and in vivo experiments suggested that miR-552-3p inhibited multiple fibrotic and inflammatory genes, and down-regulated the TGF-β1/Smad3 signaling pathway via inhibiting SMAD3 and TGFBR2, thus ameliorating liver fibrosis and inflammation." (PMID 37496991, 2023). "The results indicated that FA suppressed the expression of Smad3 induced by TGF-β1, promoted the expression of MMP-2 and MMP-9, reduced hepatocyte apoptosis, promote hepatocyte proliferation and alleviate hepatic fibrosis." (PMID 37324465, 2023). "It has been pointed out that with the aggravation of liver fibrosis, the expression of SMAD2 and SMAD3 increases." (PMID 37446187, 2023). "Among patients with liver fibrosis and hepatocellular carcinoma infected because of hepatitis B virus (HBV) infection, miR-34a-5p inhibits liver fibrosis by regulating the TGF-β1/Smad3 pathway." (PMID 36680059, 2022). "D-carvone attenuated CCl4-induced liver fibrosis by deterring oxidative stress and the TGF-ß 1/SMAD3 pathway, which presented the compound as a possible candidate for inhibiting liver fibrosis, as well as other oxidative stress-related hepatic diseases." (PMID 36294936, 2022). "TGF-βIR can phosphorylate SMAD2 and SMAD3, which suggests that phosphorylation of SMAD2 and SMAD3, is required for the smooth transmission of the TGF-β signaling pathway and thus its activation and accelerating the development of liver fibrosis." (PMID 36435779, 2022).
liver fibrosis (continued). "Glycyrrhizic acid can not only inhibit SMAD2 and SMAD3 pathways mediated by TGF-β1, but can also change the pathological morphology of the bile duct ligation model and prevent liver fibrosis." (PMID 35886594, 2022). "In carbon tetrachloride (CCl4)-induced hepatic fibrosis mice, miR-34a imbalance was also found to promote liver fibrosis via targeting Smad4 and activation TGF-β1/Smad3 pathway." (PMID 35795649, 2022). "D-carvone ameliorated the progression of liver fibrosis, evident by the decreased collagen deposition (fibrosis score) and the reduced expression of the pro-fibrogenic markers TGF-β1 and SMAD3 in the liver." (PMID 35625467, 2022). "TGF-β1 can induce TIMP-1 expression after signaling to Smad3, while inhibiting MMP-1 expression, making the ratio of TIMP-1 to MMP-1 increase, and promoting liver fibrosis." (PMID 35529927, 2022). "Smad2 and Smad3, as downstream signaling factors of TGF-β1 signaling pathway, can activate HSCs and further promote the occurrence and development of liver fibrosis." (PMID 36276815, 2022). "Liver fibrosis plays an important role in the pathogenesis of PA-induced HSOS and is closely related to the TGF-beta/p-Smad3 signaling pathway and the activation of proinflammation factors." (PMID 33679405, 2021). "miR-21 induces NASH via the STAT3 signaling pathway and induces liver fibrosis via HSC activation and collagen deposition via the TGF-β/Smad3/Smad7 signaling pathway." (PMID 34360904, 2021). "For example, miR-219 can modulate liver fibrosis by directly targeting tumor growth factor β receptor 2 (TGFBR2), while miR-34a-5p targets Smad4 and modulates TGF-β1/Smad3 pathway in HSCs to ameliorate liver fibrosis." (PMID 34161325, 2021). "During the liver fibrosis process, the expression of YAP and Smad3 tended to increase with the worsening of the disease." (PMID 34658907, 2021). "Smad3 negatively regulates the expression of miR-29b, which directly regulates TGF-β/Smad3 signaling and promotes hepatic fibrosis." (PMID 34064375, 2021). "For example, in liver fibrosis, the antifibrotic effects of propylene glycol alginate sodium sulfate involved the suppression of TGF-β1, Smad2, and Smad3." (PMID 33981353, 2021). "Naringenin at a dose of 100 mg/kg significantly reversed CCl4-induced liver fibrosis by blocking the TGF-β-Smad3 and JNK-Smad3 signaling pathways." (PMID 33082829, 2020). "In order to investigate the effect of PUM on hepatic fibrosis, we detected the hepatic mRNA expressions of TGF-β, Smad-3 and Col1-α." (PMID 32917140, 2020). "Isorhamnetin protected against liver fibrosis by reducing ECM formation and autophagy via inhibition of TGF-β1-mediated Smad3 and p38 MAPK signaling pathways." (PMID 31467486, 2019). "As shown by western blot assays and immunohistochemistry, the expression of p-Smad3 and p-p38 MAPK proteins was upregulated in liver fibrosis tissues compared with controls, while both were dose-dependently attenuated by IH." (PMID 31467486, 2019). "Based on these, this study is aimed at investigating the role of IH on CCl4- or BDL-induced mouse models of hepatic fibrosis, mainly focus on the involvement of the TGF-β1/Smad3 and TGF-β1/p38 MAPK pathway signaling and autophagy." (PMID 31467486, 2019). "Activation of PDGFRα ligands by excess PDGF-C upregulates TGFβ/Smad3 signaling to facilitate liver fibrosis and blocking of Smad3 signaling attenuates PDGF-C–induced liver fibrosis." (PMID 30509307, 2018). "Western blot analysis revealed that TGFβ1, α-SMA, p-Smad3, and p-ERK1/2 protein expression levels in DMN-induced liver fibrosis group were significantly higher than those in the control group." (PMID 30337590, 2018). "SMAD3 is a key of signal transduction pathways in liver fibrosis and elevated STAT3 phosphorylation in fibrosis is combined with TGFβ1 and SMAD3 activation." (PMID 30346985, 2018).
liver fibrosis (continued). "In this study, we found that YCHD suppresses the protein expression of TGF-β1, p-Smad3 and p-ERK1/2, whereas DMN activates TGF-β1/Smad/ERK signalling to induce liver fibrosis in rats." (PMID 30337590, 2018). "TGF-β1 has been established as the crucial fibrogenic cytokine promoting liver fibrosis, due to its activation of HSCs via TGF-β1-induced phosphorylation of receptor-activated Smad2 and Smad3." (PMID 26788244, 2016). "Smad3 is known to have the role of a transcriptional activator of the TGF-β signaling pathway, thus promoting the liver fibrosis." (PMID 26938532, 2016). "Suppression of Smad7 by DNA methyltransferase 1 promoted the phosphorylation of Smad2 and Smad3 that had been induced by HSC activation, or liver fibrosis in general." (PMID 25435153, 2015). "Recent studies have confirmed that the TGF-β1/Smad3 pathway was involved in increased deposition of fibronectin, collagen I, and α-SMA in liver fibrosis." (PMID 26378522, 2015). "The SFN incubation inhibited TGFβ1-induced SMAD3 phosphorylation in human hepatic stellate cell line, and mice treated with SFN were protected from hepatic fibrosis following bile duct ligation." (PMID 24691097, 2014). "Smad3-deficient mice are protected from diet-induced obesity and diabetes and Smad3 acts as a repressor of PGC-1α expression, thus suggesting a link between failure in mitochondrial biogenesis, metabolic syndrome, and liver fibrosis." (PMID 22745910, 2012). "A parallel mechanism has been identified in hepatic fibrosis pathogenesis, where IDO1 establishes a pro-fibrogenic positive feedback loop between hepatic stellate cells (HSCs) and Kupffer cells through upregulation of TGF-β1/Smad3 signaling." (PMID 40370742, 2025). "We showed that YQJPF attenuated CCl4-induced hepatic fibrosis and improved liver function by inhibiting inflammation, suppressing oxidative stress, regulating the immunological response initiated by macrophages, and inhibiting TGF-β/Smad3 signaling." (PMID 38434258, 2024). "Similarly, BCAAs, composed of leucine, isoleucine, and valine, regulated the expression of TGF-β1, Smad-3, α-SMA, and Smad-7 in CCl4-induced liver fibrosis rats." (PMID 38111317, 2024). "Thus, the current study provides first-hand clue in vivo evidence that DPx ameliorates hepatic fibrosis by inhibiting TGF-β1/Smad3 and MAPK signaling pathways in hepatocytes of mice administered TAA to induce liver fibrosis." (PMID 37324954, 2023). "Thus, suppression of TGF-β expression can improve hepatic fibrosis, and its mechanism of action is through the TGF-β/Smad3 signaling pathway." (PMID 37275763, 2023). "One study showed that circCREBBP inhibits liver fibrosis by binding to has-miR-129/LEFTY2, whereas another revealed that circTUBD1 has been described as a regulator in radiation-induced liver fibrosis through binding to miR-203a-3p/Smad3." (PMID 37217942, 2023). "In addition, miR-21 leads to NASH through the STAT3 signaling pathway and liver fibrosis via the activation of HSCs and the deposition of collagen through the TGF-β/Smad3/Smad7 signaling pathway." (PMID 37833930, 2023). "Moreover, SML protected against liver fibrosis in a dose-dependent manner as indicated by down-regulation of LPAR1, LPAR3, CTGF, TGF-β1/Smad3, and α-SMA expressions and a decrease in pSmad3 level, as well as an up-regulation of Smad7 expression." (PMID 35648193, 2022). "Elevated TGF-β/Smad3 pathway activity and reduced expression of miR-34a also contribute to liver fibrosis in HBV infection, whereas the over-expression of miR-34a in human hepatic stellate cells significantly attenuated fibrosis and TGF-β1/Smad3 activation by targeting Smad4." (PMID 36142450, 2022).